NUP107 (nucleoporin 107)
Description:
Plays a role in the nuclear pore complex (NPC) assembly and/or maintenance. Required for the assembly of peripheral proteins into the NPC. May anchor NUP62 to the NPC. Involved in nephrogenesis.
Synonyms: NUP84; GAMOS7; NPHS11; ODG6; ODG6; GAMOS7
Tractability: PROTAC: ubiquitination databases record sites on it; its protein half-life has been measured.
Gene: Protein-coding gene on chromosome 12 (68,686,951 to 68,745,809, forward strand). Ensembl gene ENSG00000111581.
Subcellular location: Nucleus membrane; Nucleus, nuclear pore complex; Chromosome, centromere, kinetochore
Subcellular location (Human Protein Atlas): Nucleoplasm; Centrosome; Nuclear membrane
Pathways (Reactome):
Disease: Defective TPR may confer susceptibility towards thyroid papillary carcinoma (TPC); HCMV Early Events; HCMV Late Events; NEP/NS2 Interacts with the Cellular Export Machinery; NS1 Mediated Effects on Host Pathways; Nuclear import of Rev protein; Rev-mediated nuclear export of HIV RNA; SARS-CoV-2 activates/modulates innate and adaptive immune responses; Transport of Ribonucleoproteins into the Host Nucleus; Viral Messenger RNA Synthesis; Vpr-mediated nuclear import of PICs
Cell Cycle: Amplification of signal from unattached kinetochores via a MAD2 inhibitory signal; EML4 and NUDC in mitotic spindle formation; Mitotic Prometaphase; Nuclear Pore Complex (NPC) Disassembly; Postmitotic nuclear pore complex (NPC) reformation; Resolution of Sister Chromatid Cohesion; Separation of Sister Chromatids
Metabolism of RNA: Transport of Mature mRNA Derived from an Intronless Transcript; Transport of Mature mRNA derived from an Intron-Containing Transcript; Transport of the SLBP Dependant Mature mRNA; Transport of the SLBP independent Mature mRNA; snRNP Assembly; tRNA processing in the nucleus
Metabolism of proteins: SUMOylation of DNA damage response and repair proteins; SUMOylation of DNA replication proteins; SUMOylation of RNA binding proteins; SUMOylation of SUMOylation proteins; SUMOylation of chromatin organization proteins; SUMOylation of ubiquitinylation proteins
Metabolism: IP3 and IP4 transport between cytosol and nucleus; IP6 and IP7 transport between cytosol and nucleus; IPs transport between nucleus and cytosol; Regulation of Glucokinase by Glucokinase Regulatory Protein
Cellular responses to stimuli: Regulation of HSF1-mediated heat shock response
Immune System: ISG15 antiviral mechanism
Signal Transduction: RHO GTPases Activate Formins
Gene Ontology:
Molecular function: protein binding; structural constituent of nuclear pore
Biological process: female gonad development; mRNA export from nucleus; nephron development; nuclear pore complex assembly; nucleocytoplasmic transport; post-transcriptional tethering of RNA polymerase II gene DNA at nuclear periphery; protein import into nucleus
Cellular component: kinetochore; membrane; nuclear envelope; nuclear membrane; nuclear periphery; nuclear pore; nuclear pore outer ring; cytosol
Genetic constraint (gnomAD): Loss-of-function variants: 42 observed, 65.21 expected, observed/expected ratio (o/e) 0.64, 90% interval 0.5 to 0.83. The upper end of that interval is the gene's LOEUF score, 0.83, which puts it in group 3 of 6, group 1 being the genes least tolerant of losing a copy. Missense variants: 514 observed, 612.94 expected, observed/expected ratio (o/e) 0.84, 90% interval 0.78 to 0.9. Synonymous variants: 176 observed, 209.37 expected, observed/expected ratio (o/e) 0.84, 90% interval 0.74 to 0.95.
Homologues: Orthologues: chimpanzee NUP107 (99% identical), macaque NUP107 (98% identical), pig NUP107 (95% identical), dog NUP107 (94% identical), rabbit NUP107 (94% identical), rat Nup107 (92% identical), mouse Nup107 (91% identical), guinea pig NUP107 (81% identical), tropical clawed frog nup107 (75% identical), zebrafish nup107 (67% identical), Drosophila melanogaster Nup107 (31% identical), Caenorhabditis elegans npp-5 (19% identical).